PDE4B (phosphodiesterase 4B)
Description:
Hydrolyzes the second messenger cAMP, which is a key regulator of many important physiological processes. May be involved in mediating central nervous system effects of therapeutic agents ranging from antidepressants to antiasthmatic and anti-inflammatory agents.
Synonyms: DPDE4; PDEIVB
Tractability: Small molecule: an approved drug acts on it; a structure with a bound ligand is known; a high-quality ligand is known; it has a high-quality binding pocket; it belongs to a druggable protein family. Antibody: UniProt places it where antibodies can reach, with high confidence; its Gene Ontology location is reachable by antibodies, with medium confidence. PROTAC: it is named in the literature on targeted protein degradation; ubiquitination databases record sites on it; its protein half-life has been measured; a small molecule that binds it is known.
Target class: Enzyme; Phosphodiesterase; Phosphodiesterase 4; Phosphodiesterase 4B
Chemical probes: GSK-256066 (high quality), PD081305, PD082387, PD082883, PD083054, PD084109, PD084556
Safety:
Unwanted effects reported when the protein is acted on. In parentheses: how it was acted on, where the effect was seen, and who reports it.
alcoholism (source: ClinPGx)
Gene: Protein-coding gene on chromosome 1 (65,792,514 to 66,374,579, forward strand). Ensembl gene ENSG00000184588.
Subcellular location: Cytoplasm (Isoform PDE4B5); Cell membrane
Subcellular location (Human Protein Atlas): Golgi apparatus; Cytosol; Primary cilium
Pathways (Reactome):
Signal Transduction: DARPP-32 events
Gene Ontology:
Molecular function: 3',5'-cyclic-AMP phosphodiesterase activity; cAMP binding; protein binding; 3',5'-cyclic-GMP phosphodiesterase activity; calcium channel regulator activity; transmembrane transporter binding; 3',5'-cyclic-nucleotide phosphodiesterase activity; phosphoric diester hydrolase activity
Biological process: positive regulation of interleukin-2 production; positive regulation of type II interferon production; T cell receptor signaling pathway; cellular response to epinephrine stimulus; cellular response to lipopolysaccharide; cellular response to xenobiotic stimulus; leukocyte migration; negative regulation of adenylate cyclase-activating adrenergic receptor signaling pathway; negative regulation of cAMP/PKA signal transduction; negative regulation of relaxation of cardiac muscle; neutrophil chemotaxis; neutrophil homeostasis; regulation of calcium ion transmembrane transport via high voltage-gated calcium channel; regulation of cardiac muscle cell contraction; cAMP catabolic process; signal transduction
Cellular component: cytoplasm; cytosol; plasma membrane; voltage-gated calcium channel complex; Z disc
Genetic constraint (gnomAD): Loss-of-function variants: 14 observed, 58.53 expected, observed/expected ratio (o/e) 0.24, 90% interval 0.16 to 0.37. The upper end of that interval is the gene's LOEUF score, 0.37, which puts it in group 1 of 6, group 1 being the genes least tolerant of losing a copy. Missense variants: 539 observed, 768.79 expected, observed/expected ratio (o/e) 0.7, 90% interval 0.65 to 0.75. Synonymous variants: 273 observed, 277.12 expected, observed/expected ratio (o/e) 0.99, 90% interval 0.89 to 1.09.
Homologues: Orthologues: chimpanzee PDE4B (99% identical), macaque PDE4B (99% identical), rabbit PDE4B (98% identical), pig PDE4B (97% identical), mouse Pde4b (97% identical), rat Pde4b (97% identical), dog PDE4B (97% identical), guinea pig PDE4B (95% identical), tropical clawed frog pde4b (85% identical), zebrafish pde4ba (74% identical), zebrafish pde4bb (71% identical), Drosophila melanogaster dnc (58% identical), and 1 more. Paralogues in human: PDE4D (70% identical), PDE4A (69% identical), PDE4C (59% identical), PDE8B (21% identical), PDE1C (21% identical), PDE3A (21% identical), PDE1B (20% identical), PDE8A (20% identical), PDE3B (20% identical), PDE6C (20% identical), PDE1A (19% identical), PDE11A (19% identical), and 8 more.
Diseases named in the same sentence as PDE4B in open-access papers:
PDE4B is named in the same sentence as 145 diseases in open-access papers, as found by Europe PMC text mining. Sharing a sentence is not in itself a finding about the gene and the disease. The quoted sentences say what the papers report.
schizophrenia (30 papers, 2007 to 2024). A major psychotic disorder characterized by abnormalities in the perception or expression of reality. "Overall, while there is support for the causal role of PDE4B downregulation in schizophrenia, preceding symptom onset, other studies present a different perspective." (PMID 38790238, 2024). "First, PDE4B-related SNPs were associated with schizophrenia, supporting PDE4B involvement in disease development." (PMID 38790238, 2024). "PDE4B encodes a protein that specifically hydrolyzes cAMP; the altered activity of this protein has been associated with schizophrenia and bipolar disorder." (PMID 35656316, 2022). "CpG sites conforming the black module were enriched in morphine addiction (GABBR2, GABRP and PDE4B), and polymorphisms of the PDE4B gene have been associated with susceptibility to schizophrenia." (PMID 34579086, 2021). "This notion was supported by recent work suggesting that novel single nucleotide polymorphisms (SNPs) in PDE4B are associated with an increase incidence of schizophrenia within the general population." (PMID 32438615, 2020). "Genetic association of the 3’ end of the PDE4B gene with schizophrenia was replicated in Japanese and Han Chinese." (PMID 30800055, 2019). "Correlation between PDE4B gene polymorphism and schizophrenia was demonstrated, and so was the correlation with bipolar disorder and depression." (PMID 31663033, 2019). "PDE4B gene variants previously were linked to risk for schizophrenia in a study of 878 schizophrenic or schizoaffective patients and 604 controls that included both Caucasian and African American subjects." (PMID 30800055, 2019). "Genetic variation in PDE4B has been linked to schizophrenia, while ACRYDS2 mutations in PDE4D severely affect cognitive function." (PMID 30800055, 2019). "DISC1 is known to interact via its N-terminal globular domain with PDE4B, mutation of which has previously been implicated in neurodevelopmental disorders such as schizophrenia." (PMID 28334933, 2017). "Although anestablished rare genetic cause of schizophrenia, emerging primate data providepreliminary support for a role for PDE4B in the regulation of synaptic and spineplasticity in the dorsolateral prefrontal cortex and working memory." (PMID 26272049, 2016). "The only meta-analysis concerning the association of PDE4B SNPs and schizophrenia was taken in Bae’s study, which just combined Korean population in their own study and Japanese population in Numata’s study." (PMID 26756575, 2016). "In order to better understand the genetic role of PDE4B for schizophrenia susceptibility, we recapitulated the association of different PDE4B SNPs with schizophrenia risk in multi-ethnic populations under allelic, dominant and recessive models." (PMID 26756575, 2016). "This meta-analysis suggests that PDE4B SNPs are genetically associated with susceptibility to schizophrenia." (PMID 26756575, 2016). "Several lines of evidence have implicated PDE4B in major psychiatric illness, mostnotably schizophrenia." (PMID 26272049, 2016). "The PDE4B single nucleotide polymorphisms (SNPs) have been reported to be associated with schizophrenia risk." (PMID 26756575, 2016). "To better facilitate the understanding the genetic role played by PDE4B in susceptibility to schizophrenia, we collected currently available data and conducted this meta-analysis." (PMID 26756575, 2016). "The association between PDE4B SNPs and schizophrenia was evaluated by odds ratios (ORs) and 95% confidence intervals (CIs) under allelic, dominant and recessive genetic models." (PMID 26756575, 2016). "Two allelic haplotypes of PDE4B were observed in statistical significance (P = 0.0022 and P = 0.029), increasing or decreasing schizophrenia susceptibility." (PMID 26756575, 2016). "PDE4B was initially reported as a genetic susceptibility factor for schizophrenia in the exploration of chromosomal abnormalities of two psychiatric cousins." (PMID 26756575, 2016).
schizophrenia (continued). "Since PDE4B was first suggested as a risk factor for schizophrenia, PDE4B has also been suggested as a candidate gene associated with both schizophrenia and bipolar disorder." (PMID 21311593, 2011). "Moreover, expression quantitative trait loci (eQTLs) and colocalization analysis identified several schizophrenia risk variants in PDE4B that were associated with reduced PDE4B expression in both excitatory and inhibitory neurons and glial cells." (PMID 38790238, 2024). "To explore the potential association between PDE4B downregulation and schizophrenia symptoms, we examined whether existing PDE4B inhibitors exert adverse effects resembling schizophrenia symptoms." (PMID 38790238, 2024). "If variant monomeric forms of PDE4B are causal in schizophrenia, their expression in brain microglia could be relevant to the etiology of the disease though an effect on synaptic pruning." (PMID 30800055, 2019). "Similarly, human PDE4D haplotypes and single-nucleotide polymorphisms (SNPs) correlate with ischemic stroke, and PDE4B SNPs are associated with schizophrenia." (PMID 29088834, 2017). "Besides the studies included into our meta-analysis, there are some other studies demonstrating the genetic association between PDE4B SNPs and schizophrenia." (PMID 26756575, 2016). "However, due to limitations in our meta-analysis, more large-scale studies from different ethnic populations are needed to further ascertain the underlying relationship between PDE4B SNPs and predisposition to schizophrenia." (PMID 26756575, 2016). "Overall analysis of association of PDE4B SNP with schizophrenia risk." (PMID 26756575, 2016). "Additionally, PDE4B is implicated in schizophrenia, whereas DAB1 truncated in our patient is required for synaptic function as well as associative learning in mice, and has been shown to be associated with autism." (PMID 26997977, 2016). "PDE4B was first implicated as a candidate risk gene for schizophrenia through investigating chromosomal abnormalities of two cousins, the proband of whom was diagnosed with schizophrenia." (PMID 26756575, 2016). "However, due to limited sample size, more large-scale, multi-racial association studies are needed to further clarify the genetic association between various PDE4B variants and schizophrenia." (PMID 26756575, 2016). "Furthermore, a candidate gene association study based on Finnish pedigrees identified that the PDE4B SNP rs7412571 was significantly associated with schizophrenia (P = 0.018)." (PMID 26756575, 2016). "However, there are biologically interesting genes related to brain volumes including PDE3A, previously related to all aspects of thrombosis, SCN8A linked to cerebellar ataxia with mental retardation, and PDE4B which has been associated with schizophrenia." (PMID 17903297, 2007). "Though there have been numerous association studies examining the genetic role of PDE4B in the etiology of schizophrenia, to date to our knowledge, no comprehensive meta-analysis was conducted to systematically summarize the association of PDE4B polymorphisms and schizophrenia." (PMID 26756575, 2016). "For PDE4B, two of the datasets showed significant downregulation in schizophrenia after accounting for age, pH, and PMI potential effects (Chen 2013, p-value < 0.001; Stanley#6, p-value = 0.03)." (PMID 38790238, 2024). "Based on mRNA expression levels of 437 brain samples (219 schizophrenia and 218 controls), the results reveal significant downregulation of PDE4B in brain samples of individuals with schizophrenia compared to healthy controls." (PMID 38790238, 2024). "This further strengthened the significance of PDE4B downregulation in brain samples of patients with schizophrenia (p-value = 0.01)." (PMID 38790238, 2024). "The analysis of the large CMC DLPFC dataset (515 samples) further validated PDE4B downregulation in schizophrenia." (PMID 38790238, 2024).
schizophrenia (continued). "Since GWAS data have associated PDE4B with PTSD and schizophrenia, which are often comorbid, we subjected Pde4bM220T mice to several behavioral tests that examine a range of evolutionary conserved cognitive and behavioral domains." (PMID 39256048, 2024). "The authors reported in vitro activities of these compounds against phosphodiesterase 4B protein (PDE4B), a gene family that plays a role in the treatment of schizophrenia." (PMID 34577138, 2021). "Initial genetic evidence for PDE4B‘s role in Schizophrenia was discovered in two cousins, both harboring the same translocation disrupting PDE4B and been diagnosed with the psychiatric disorder." (PMID 32438615, 2020). "The phosphodiesterase 4B (PDE4B) was found to be involved in cognitive function in animal models and serves as a susceptibility gene for bipolar disorder and schizophrenia." (PMID 31114610, 2019). "There was a report regarding a patient with schizophrenia and his relative with a chronic psychiatric disorder who were found to have a balanced translocation impairing the PDE4B gene structure." (PMID 31663033, 2019). "The expression of PDE4B isoforms assessed post mortem in the brain of patients with schizophrenia and bipolar disorder differs from that in the control group." (PMID 31663033, 2019). "In addition, these significantly schizophrenia-associated SNPs are mostly located in introns adjacent to splice junctions, which indicates that genetic variants in introns surrounding critical splice junctions within the PDE4B gene are associated with increased incidence of schizophrenia." (PMID 26756575, 2016). "Among various candidate genes for schizophrenia, the gene phosphodiesterase 4B (PDE4B), which is located on human chromosome 1 at 1p31 and composed of 17 exons spanning 580 kb, belongs to PDE4 families." (PMID 26756575, 2016). "Disruption of PDE4B was identified by a chromosomaltranslocation in two first cousins with schizophrenia (Millaret al, 2005)." (PMID 26272049, 2016). "We previously identified disruption of PDE4B in two cousins, one diagnosed with schizophrenia and the other with psychosis." (PMID 26388333, 2015). "In the Disc1 mutant mouse, L100P, which lies with a missense PDE4B-specific binding site in exon 2, rolipram treatment improves the behavioural and cognitive deficits seen in this model of schizophrenia." (PMID 21298101, 2011). "Additionally, the analysis of blood samples from affected individuals reveals downregulation of PDE4A and upregulation of PDE4B, suggesting their potential as biomarkers for schizophrenia." (PMID 38790238, 2024). "However, there is substantial evidence for the involvement of genetic variations of PDE4B in the pathophysiology of schizophrenia and other psychiatric disorders, emphasizing the importance of a systematic study of its differential expression in schizophrenia." (PMID 38790238, 2024). "Relatively few studies have previously examined PDE4B expression in schizophrenia." (PMID 38790238, 2024). "PDE4B was found to be downregulated in schizophrenia (p-value = 0.029)." (PMID 38790238, 2024). "Large-scale genome-wide association studies (GWASs) have associated intronic variants in PDE4B, encoding cAMP-specific phosphodiesterase-4B (PDE4B), with increased risk for post-traumatic stress disorder (PTSD), as well as schizophrenia and substance use disorders that are often comorbid with it." (PMID 39256048, 2024). "Indeed, GWASs have associated PDE4B SNPs with PTSD, as well as schizophrenia and substance use disorders that are often comorbid with it." (PMID 39256048, 2024). "It should be taken into account that the decrease in PDE4B levels seen in schizophrenia patients’ brains may be a compensatory response to aberrant cAMP signaling." (PMID 38790238, 2024). "The main question is whether and how PDE4B downregulation contributes to the development of schizophrenia and affects LTP and memory formation processes in a subset of the patients." (PMID 38790238, 2024).
schizophrenia (continued). "In a GWAS of schizophrenia, PDE4B was 1 of 106 protein-coding genes prioritized as likely causal." (PMID 39256048, 2024). "However, a study detected decreased PDE4B protein levels in brain samples of individuals with schizophrenia." (PMID 38790238, 2024). "Interestingly, PDE4B was found to be upregulated in blood samples of patients with schizophrenia (p-value = 0.0011), while PDE4A was found to be downregulated (p-value = 0.0052)." (PMID 38790238, 2024). "Reduction in the levels of PDE4B in the postmortem brains of schizophrenia patients prompted the question whether PDE4B may be a common component in a variety of neurological disorders." (PMID 32438615, 2020). "Furthermore, emerging evidence of genetic association (NDEL1, PCM1, PDE4B) and copy number variation (NDE1) implicate several DISC1-binding partners as risk factors for schizophrenia in their own right." (PMID 21195721, 2012). "Thus, in much the same way as DISC1 was discovered at a translocation breakpoint, PDE4B was found to be directly disrupted by a t(1:16) translocation in a proband with schizophrenia, who also had an affected cousin." (PMID 21195721, 2012). "However, psychotic schizophrenia-like symptoms have also been noted amongst Huntington's disease patients consistent with the interaction of huntingtin with proteins from other schizophrenia-associated genes such as PCM1, PDE4B and DPYSL2." (PMID 21298101, 2011). "Of the various PDE4 isoforms, those encoded by PDE4B have been most closely associated with schizophrenia and major affective disorders and have been shown to interact directly with DISC1, a protein implicated in neurodevelopment, nuclear functions, and susceptibility to schizophrenia in humans." (PMID 32784895, 2020). "PDE4B has also been shown to interact with DISC1, a protein that plays an important role in synaptic plasticity and is a potential susceptibility factor for mental disorders, including schizophrenia, schizoaffective disorder, bipolar disorder, depression and anxiety." (PMID 31663033, 2019). "In addition, disrupted in schizophrenia 1 (DISC1), another putative susceptibility factor for schizophrenia, was identified to interact with UCR2 domain of PDE4B and elevated cAMP contributed to decreased binding of PDE4B to DISC1 and an increase in PDE4B activity." (PMID 26756575, 2016). "We next explored whether PDE4A, PDE4B, PDE4C, and PDE4D are differentially expressed not only in the brain samples but also in blood samples of patients with schizophrenia and thus might serve as biomarkers." (PMID 38790238, 2024). "Besides the downregulation of PDE4B in brain samples, PDE4A was downregulated in blood samples from schizophrenia patients." (PMID 38790238, 2024). "Five of these top eight LD-independent loci (MTHFR, PDE4B, DAOA, ARVCF, TRAM1L1/NDST3) were not located within risk loci identified in the largest schizophrenia GWA study produced by the PGC and three loci (MTHFR, DAOA, ARVCF) had never been implicated by a schizophrenia GWA study." (PMID 31455759, 2019).